GSKIP (GSK3B interacting protein)
Description:
A-kinase anchoring protein for GSK3B and PKA that regulates or facilitates their kinase activity towards their targets. The ternary complex enhances Wnt-induced signaling by facilitating the GSK3B- and PKA-induced phosphorylation of beta-catenin leading to beta-catenin degradation and stabilization respectively. Upon cAMP activation, the ternary complex contributes to neuroprotection against oxidative stress-induced apoptosis by facilitating the PKA-induced phosphorylation of DML1 and PKA-induced inactivation of GSK3B. During neurite outgrowth promotes neuron proliferation; while increases beta-catenin-induced transcriptional activity through GSK3B kinase activity inhibition, reduces N-cadherin level to promote cell cycle progression.
Synonyms: C14orf129; HSPC210
Tractability: PROTAC: its protein half-life has been measured.
Gene: Protein-coding gene on chromosome 14 (96,363,452 to 96,387,288, forward strand). Ensembl gene ENSG00000100744.
Subcellular location: Cytoplasm; Nucleus
Subcellular location (Human Protein Atlas): Golgi apparatus; Vesicles; Nucleoli
Gene Ontology:
Molecular function: beta-catenin binding; protein binding; protein kinase A binding; protein kinase A regulatory subunit binding; protein kinase binding; protein kinase inhibitor activity; kinase regulator activity
Biological process: intrinsic apoptotic signaling pathway in response to oxidative stress; negative regulation of protein kinase activity; positive regulation of canonical Wnt signaling pathway; regulation of Wnt signaling pathway; regulation of canonical Wnt signaling pathway
Cellular component: cytoplasm; nucleus
Genetic constraint (gnomAD): Loss-of-function variants: 3 observed, 9.02 expected, observed/expected ratio (o/e) 0.33, 90% interval 0.15 to 0.86. That is too few expected variants to judge how well the gene tolerates losing a copy. Missense variants: 126 observed, 144.5 expected, observed/expected ratio (o/e) 0.87, 90% interval 0.75 to 1.01. Synonymous variants: 59 observed, 56.24 expected, observed/expected ratio (o/e) 1.05, 90% interval 0.85 to 1.3.
Homologues: Orthologues: chimpanzee GSKIP (100% identical), macaque GSKIP (100% identical), mouse Gskip (94% identical), rat Gskip (94% identical), pig GSKIP (93% identical), dog GSKIP (92% identical), guinea pig GSKIP (91% identical), tropical clawed frog gskip (73% identical), zebrafish gskip (66% identical), Caenorhabditis elegans Y43F8B.2 (32% identical), Drosophila melanogaster CG11523 (29% identical), Caenorhabditis elegans lelo-1 (28% identical), and 2 more.
Diseases named in the same sentence as GSKIP in open-access papers:
GSKIP is named in the same sentence as 12 diseases in open-access papers, as found by Europe PMC text mining. Sharing a sentence is not in itself a finding about the gene and the disease. The quoted sentences say what the papers report.
hepatocellular carcinoma (2 papers, 2021). A malignant tumor that arises from hepatocytes. "In addition, it has been reported that the overexpression of OTUD6B-AS1 makes hepatocellular carcinoma cells more aggressive through the GSKIP/Wnt/β-catenin signaling pathway." (PMID 34671639, 2021). "In contrast, in hepatocellular carcinoma (HCC), OTUD6B-AS1 could enhance cell proliferation and invasion ability via the GSKIP/Wnt/β-catenin signaling pathway." (PMID 34977036, 2021).
neuroblastoma (2 papers, 2019 to 2023). Neuroblastoma (NB) is the most common solid, extracranial childhood tumor. "We recently identified residue L130 of GSKIP as a critical point for binding with GSK3β, and the L130P GSKIP mutant resulted in loss of inhibition of neurite outgrowth in human neuroblastoma SH-SY5Y cells." (PMID 31640277, 2019). "In this study, we identified a specific PKA phosphorylation site on Tau protein that was accompanied by GSK3β and GSKIP to form a working complex from the neuroblastoma cell line in clinical AD patients." (PMID 31640277, 2019). "We previously identified residue L130 of GSKIP as being critical for binding with GSK3β, and cells with the L130P GSKIP mutant lose the inhibition of neurite outgrowth in human SH-SY5Y neuroblastoma cells." (PMID 31640277, 2019).
cervical squamous cell carcinoma (1 paper, 2022). A squamous cell carcinoma arising from the cervical epithelium. "Moreover, miR-181c-5p could mitigate carcinogenesis in cervical squamous cell carcinoma via GSKIP." (PMID 35251139, 2022).
myeloid malignancies (1 paper, 2022). "Genetic analyses of the families revealed that germ line duplication of ATG2B and GSKIP conferred a risk of familial myeloid malignancies, and overexpression of ATG2B and GSKIP in HSCs enhanced hematopoietic progenitor differentiation." (PMID 34748402, 2022).
myeloproliferative neoplasm (1 paper, 2022). A clonal hematopoietic stem cell disorder, characterized by proliferation in the bone marrow of one or more of the myeloid (i.e., granulocytic, erythroid, megakaryocytic, and mast cell) lineages. "A germ line copy number duplication of chromosome 14q32, which contains ATG2B and GSKIP, was identified in families with myeloproliferative neoplasm (MPN)." (PMID 34748402, 2022).
non-small cell lung carcinoma (1 paper, 2022). A group of at least three distinct histological types of lung cancer, including non-small cell squamous cell carcinoma, adenocarcinoma, and large cell carcinoma. "A recent study showed that miR-150-5p significantly inhibited Wnt-β-catenin signaling by simultaneously targeting GSKIP and β-catenin in non-small-cell lung cancer (NSCLC) cells." (PMID 35051222, 2022).
small cell lung carcinoma (1 paper, 2025). Small cell lung cancer (SCLC) is a highly aggressive malignant neoplasm, accounting for 10-15% of lung cancer cases, characterized byrapid growth, and early metastasis. "A previous study identified that LINC00173 suppressed miR-218 in small cell lung cancer (SCLC) and upregulated N-myc downstream-regulated gene 1 (NDRG1) and GSK3β-interacting protein (GSKIP)." (PMID 40251826, 2025).
tumor (4 papers, 2020 to 2024). "GSKIP acts as a negative regulator of GSK3β in the Wnt signaling pathway, influencing vital cellular processes like differentiation, proliferation, and tumor formation." (PMID 39192051, 2024). "Lastly, five genes including GSKIP, SELENOF, RAP1B, UBE2D3, and GTF2B, were found to be co-expressed in both adjacent healthy tissue and tumor tissue." (PMID 37365287, 2023). "The authors determined HANR to be capable of binding GSKIP, thereby controlling GSK3β phosphorylation in HCC, potentially thereby promoting tumor growth." (PMID 32049807, 2020). "However, other studies report that miR-150-5p inhibits Wnt-β-catenin signaling via targeting GSKIP and HMGA2, or suppresses MMP14, or GLUT1 to exert its tumor-suppressive properties in NSCLC." (PMID 34193018, 2021).
GSKIP also shares sentences with these, for which no sentence is quoted: Alzheimer disease (1 paper); anemia (1); cervical cancer (1); tauopathies (1).